PECAM1 (platelet and endothelial cell adhesion molecule 1)
Diseases named in the same sentence as PECAM1 in open-access papers (continued):
Sharing a sentence is not in itself a finding about the gene and the disease.
glioma (103 papers, 2006 to 2025). A benign or malignant brain and spinal cord tumor that arises from glial cells (astrocytes, oligodendrocytes, ependymal cells). "We analyzed AngioMatrix expression in independent glioma datasets and observed again a significant correlation between AngioMatrix expression and the EC markers PECAM1 and CDH5." (PMID 25301723, 2014). "To test this possibility, we assessed CD31 (PECAM-1)-labeled blood capillaries within Hu-gliomas that were allowed to progress until neurological symptoms developed, facilitating an analysis of tumors of comparable size." (PMID 22905089, 2012). "NES, CD34 nor PECAM1 expression was associated with prognosis in urothelial cancer, lung cancer, stomach cancer or glioma." (PMID 30279450, 2018). "To visualize tumor cells in the brain, we implanted citrine-expressing mouse glioma cells (GL26-Cit-NT or GL26-Cit-sh2CXCR4) into the striatum of NSG mice (N=5/group) and then labeled the tumor-associated blood vessels with anti-CD31 (anti-PECAM-1)-antibody." (PMID 27863376, 2016). "We found that in a syngeneic mouse model of glioma (K-luc), ICG-001 treatment enhanced tumor infiltration by CD3+ and CD8+ cells with increased expression of the vascular endothelial marker CD31 (PECAM-1)." (PMID 38449858, 2024). "In addition, while the high expression of PECAM1/CD31 is related to the better prognosis of patients with kidney renal clear cell carcinoma, and skin cutaneous melanoma, the high expression of PECAM1/CD31 is related to the poor prognosis of patients with brain low grade glioma and uveal melanoma." (PMID 31850854, 2019).
Stroke (90 papers, 2003 to 2026). Sudden impairment of blood flow to a part of the brain due to occlusion or rupture of an artery to the brain. "The volcano plot indicates significant downregulation of genes already implicated in inflammation and apoptotic cell death following stroke such as Ccr5, Casp8, Icam2, Mmp9, Pecam1, and Il6." (PMID 39000490, 2024). "Similar analysis of genes in the Disease and Function categories indicated that female MMP-3 KO stroke brains had decreased expression of leukocyte migration genes Ccr1, Pecam1, Mmp9, Ccl6, Icam2, and Ccl11." (PMID 39000490, 2024). "Female MMP-3 KO stroke brains also had decreased expression of blood cell adhesion genes Pecam1 and Icam2, and decreased expression of inflammatory response genes Ccr1, Cxcl1, Mmp9, Il4ra, Il6, and Il1rn." (PMID 39000490, 2024). "Labeling of proliferating cells one week after stroke using 5-ethynyl-2’-deoxyuridine (EdU) injections combined with immunofluorescent labeling of PECAM1+ ECs showed that Apold1−/− ECs within the ischemic border zone proliferate less." (PMID 36933174, 2023). "CD31 (PECAM-1) antigen is expressed on ECs and pericytes, and is considered a marker of post-stroke angiogenesis." (PMID 24672479, 2014). "qPCR of RiboTag-IP’dmRNA from isolated microvessels after stroke revealed enrichment of astrocyte markers Aqp4 and Gfap, as well as depletion of vascular markers including Pecam1, Cldn5 (endothelial cells), Pdgfrb (pericytes), and Acta2 (vascular smooth muscle cells)." (PMID 39796165, 2025). "However, since the RECA-1 antibody stains all blood vessels, perhaps CD31 (PECAM-1) staining would have revealed post-stroke angiogenesis." (PMID 30972000, 2019). "Similarly, genes involved in integrin cell surface interactions including Itga10, Itgb3, Vcam1, Itgb1, Itgae, Itgb7, Itga1, Itga5, Icam1, Itgb2, Pecam1, and Icam2 were depleted in male MMP-3 KO stroke brains." (PMID 39000490, 2024). "Clustering analysis of DEGs in male and female stroke brains revealed that MMP-3 KO decreased expression of genes that belong to the adhesion and leukocyte extravasation pathway such as Esam, Icam1, Icam2, Mcam1, and Pecam1." (PMID 39000490, 2024). "In one experimental study, PECAM-1 was found to control the transendothelial migration of neutrophils in a experimental mouse model of ischemic stroke, and antibody blockade of PECAM-1 during reperfusion ameliorated stroke severity in these mice." (PMID 34868060, 2021).
diabetes (71 papers, 2005 to 2026). "Type 2 diabetes mellitus has been shown to be associated with the cleavage of platelet PECAM-1." (PMID 20040043, 2010). "Alternatively, PECAM-1 expression at additional time points after the onset of diabetes should be investigated in future studies." (PMID 38748682, 2024). "Previous works have reported that PECAM-1 is an important feature of differentiated VSMCs, whereas the hypercontractility phenotype of differentiated VSMCs usually seen in diabetes and hypertension was correlated with RhoA upregulation." (PMID 36292250, 2022). "A previous study indicated that diabetes induced a significant decrease in PECAM-1 expression in the retina of db/db mice." (PMID 34445504, 2021). "For example, Sakaue and associates found no change in PECAM-1 immunofluorescence signal in retinal vasculature between prediabetic state and 9 months after diabetes in a STZ mouse model." (PMID 38748682, 2024). "This does not support a strong association between PECAM-1 loss and vascular permeability in the retina in early diabetes." (PMID 38748682, 2024). "PECAM-1 level was unchanged in the retina at 2 months of diabetes." (PMID 38748682, 2024). "Few studies have investigated the regulation of CRIF1 and PECAM-1 in the cochlea in diabetes." (PMID 34445504, 2021). "In addition, chrysin increased the expression of the endothelial cell-cell adhesion molecule PECAM-1 diminished in diabetic retina." (PMID 27918469, 2016). "In addition, chrysin restored the decrement of VE-cadherin and ZO-1 junction proteins and PECAM-1 in hyperglycemia-stimulated retinal endothelial cells and diabetic mouse retina, possibly maintaining tight cell-cell interactions of endothelial cells and pericytes." (PMID 27918469, 2016). "For islet vascular damage in diabetes, neutrophil transmigration across TNF-activated endothelial monolayers can be accelerated by co-clustering L-selectin with PECAM-1." (PMID 36527108, 2022). "Platelet/endothelial cell adhesion molecule 1 (Pecam1) is a glycoprotein located near a QTL for fatty liver and diabetes." (PMID 24499025, 2014). "Our results corroborate these findings and do not suggest a change of PECAM-1 protein level in ECs during early diabetes." (PMID 38748682, 2024). "However, comparable levels of PECAM1, CXCR2, SLC2A3, BST2, S100A11, S100A12, and CPNE3 were found in neutrophils from diabetes patients and controls (P > 0.05)." (PMID 32377527, 2020). "Moreover, several other genes between PECAM-1 and Igf2Bp1, such as Growth Hormone, STAT3, and STAT5 are involved in diabetic nephropathy or diabetes and an identified IDD4 interval spans STAT3." (PMID 16371158, 2005). "Similarly, we found no changes in PECAM-1 mRNA and protein levels between WT and cKO mouse BMECs regardless of the presence of diabetes." (PMID 38748682, 2024). "Second we did not investigate PECAM-1 changes in diabetic mice beyond 2 months of diabetes." (PMID 38748682, 2024). "Furthermore, PECAM-1 mRNA and protein expression was unchanged in BMECs isolated from cKO mice compared to wild type (WT) mice with or without 2 months of diabetes." (PMID 38748682, 2024). "To investigate if Nox4 regulates PECAM-1 expression in diabetic conditions, we induced diabetes in cKO mice and isolated BMECs from non-diabetic and diabetic cKO and WT mice after 2 months of diabetes." (PMID 38748682, 2024). "The lack of change in PECAM-1 protein level in the retina or ECs of diabetic mice at 2 months or 9 months of diabetes, as observed in this study and by others, may suggest discrepancies in mouse and rat DR models." (PMID 38748682, 2024).
atherosclerosis (67 papers, 2009 to 2025). A disease characterized by the build-up of fatty material and calcium deposition in the arterial wall resulting in partial or complete occlusion of the arterial lumen. "PECAM-1 has been involved in the pathophysiology of inflammation, coagulation, and atherosclerosis, and NECTIN-2 has been associated to atherogenesis." (PMID 38673963, 2024). "Since endothelial dysfunction marked by impaired vasodilation is a risk for atherosclerosis, functional PECAM-1 and eNOS are essential for normal coronary artery physiology and CHD prevention." (PMID 36292250, 2022). "Previous studies reported that PECAM-1 polymorphisms have been associated with coronary artery stenosis or atherosclerosis." (PMID 28512385, 2017). "Moreover, genetic deletion of PECAM1 in apolipoprotein E deficient (apoE–/–) mice showed a significant decrease in atherosclerosis development compared to apoE–/– controls." (PMID 35694160, 2022). "Polymorphism of PECAM1 is associated with the incidence rate of coronary atherosclerosis, indicating that inflamm-aging could accelerate atherosclerosis progression." (PMID 35706446, 2022). "PECAM-1 has been implicated in the maintenance of vascular barrier integrity; failure to restore barrier function contributes to the development of chronic inflammatory diseases such as atherosclerosis." (PMID 30678728, 2019). "Platelet endothelial cell adhesion molecule-1 (PECAM-1/CD31), involved in leukocyte transmigration and angiogenesis, is also implicated in plaque formation, thrombosis, and the development of atherosclerosis." (PMID 38638292, 2024). "Several studies have demonstrated that genetic variations in the PECAM1 gene can affect the progression of atherosclerosis in the coronary and carotid arteries." (PMID 37834987, 2023). "Several mechanisms that connect shear stress and atherosclerosis have been described, involving PECAM-1, eNOS, and RhoA." (PMID 36292250, 2022). "In the KEGG signaling pathway analysis of DEGs, we found that RES was associated with fluid shear stress and atherosclerosis, including VCAM1, ICAM1, PECAM1, and other adhesion molecules closely related to atherosclerosis." (PMID 36364780, 2022). "The activation of endothelial PECAM1 has been shown to lead to nuclear translocation of nuclear factor κB (NF-κB) and expression of inflammatory and adhesion mediators, which promoted atherosclerosis." (PMID 35706446, 2022). "Other potential markers including HEY2 (identified by sensitivity analysis) and PECAM1 (identified by MR and sensitivity analysis) and the top causal pairs BIRC2–PLOD1 and CRBN–MRPL40 also suggested a role of immunity in atherosclerosis." (PMID 35706446, 2022). "PECAM-1 is vital to the regulation of inflammatory responses, and inhibition of PECAM1 has been documented to alleviate symptoms of several inflammatory diseases such as arthritis, atherosclerosis, and pulpitis." (PMID 36148415, 2022). "For instance, the platelet and cell adhesion molecule PECAM1 is essential for vascular remodeling in mice with PECAM1 knockout mice, which are partially protected from atherosclerosis, exhibiting reduced aortic arch and sinus lesions." (PMID 31086124, 2019). "Here we found that IL-27R signaling during the early phase of atherosclerosis development is implicated into the regulation of the adhesion molecules VCAM-1, P-selectin, E-selectin and PECAM-1 expression by vascular endothelial cells." (PMID 28536468, 2017). "ICAM and PECAM1 molecule are involved in adhesion of monocytes and other immune cells in atherosclerosis." (PMID 27255968, 2016). "Low shear stress (LSS) plays a critical role in the site predilection of atherosclerosis through activation of cellular mechanosensors, such as platelet endothelial cell adhesion molecule 1 (PECAM-1)." (PMID 25793984, 2015).
atherosclerosis (continued). "Additionally, F. nucleatum infection has been shown to decrease the expression of platelet endothelial cell adhesion molecule-1 (PECAM-1) and induce endothelial cell death, further contributing to vascular pathology and the development of atherosclerosis." (PMID 40136726, 2025). "PECAM1 has widespread effects on vascular biology and atherosclerosis in particular." (PMID 36131068, 2022). "On the other hand, the suppression of PECAM-1 expression in AEC observed in our experiments may slow down the progression of atherosclerosis." (PMID 33641611, 2021). "Moreover, common variants assigned to PECAM1 in humans have been associated with CAD in a large GWAS, highlighting the role of PECAM-1 in atherosclerosis beyond its known effects in cell culture and mouse models." (PMID 35087886, 2021). "It is reported that in an inflammatory condition, such as in vessels affected by atherosclerosis, the function of PECAM-1 is compromised which can lead to augmented adhesion of immune cells to EC, diminished vascular integrity, and greater leukocyte transmigration to the intima-media." (PMID 33841078, 2021). "PECAM1+ cells may contribute to the suppression of inflammatory processes driving atherosclerosis." (PMID 36131068, 2022). "However, the role of PECAM-1—although quite obviously promoting leukocyte transmigration in vitro—seems to be more complex in atherosclerosis in general, as it exerts different influences on atherogenesis partly depending on the hemodynamic environment (see section Keep it Flowing)." (PMID 35087886, 2021). "Therefore, the atherogenic effect of PECAM-1 may be attributed to platelet adhesion, and the adhered platelets recruit circulating leukocytes to promote vascular inflammation and atherosclerosis." (PMID 33371312, 2020). "CD31, known as platelet endothelial cell adhesion molecule-1(PECAM-1), expresses on the surface of endothelial cells, acting as a signaling receptor and stimulating the expression of inflammatory molecules on atherosclerosis lesions." (PMID 39337364, 2024). "There are many key molecules involved in the laminar shear stress and atherosclerosis pathways, such as endothelin 1 (EDN1), vascular cell adhesion molecule 1 (VCAM1), KLF2, intercellular adhesion molecule 1 (ICAM1), and platelet and endothelial cell adhesion molecule 1 (PECAM1)." (PMID 36364780, 2022). "PECAM-1 is also an important factor in atherosclerosis, as a lack of PECAM-1 in ApoE−/− mice will significantly reduce the lesion size of the aortic arch and aortic sinus." (PMID 33371312, 2020). "Various antibody-based or peptide-based theranostic nanocarriers targeting VCAM-1, ICAM-1, E- and P-selectin, or platelet endothelial cell adhesion molecule (PECAM-1) are described in the literature to deliver their cargo to endothelial cells in in vitro and in vivo models of atherosclerosis." (PMID 31382634, 2019).
endothelial dysfunction (62 papers, 2012 to 2025). In vascular diseases, endothelial dysfunction is a systemic pathological state of the endothelium (the inner lining of blood vessels) and can be broadly defined as an imbalance between vasodilating and vasoconstricting substances produced by (or acting on) the endothelium. "The chemokine CCL2, which is elevated during CNS inflammation and is associated with endothelial dysfunction, transiently induces Src-dependent disruption of hCMEC/D3 AJs, translocation of β-catenin from the AJ to PECAM-1, and increases surface localization of PECAM-1." (PMID 23531482, 2013). "SERPINH1 (rs590121 lead SNP) is predicted to increase risk of hemorrhage; DDX59-CAMSAP2 (rs1867624) may be involved abnormal vascular development; PECAM1 (rs1867624) may regulate vascular inflammation and endothelial dysfunction; and LMOD1 (rs2820315) is implicated in SMC differentiation." (PMID 30444878, 2018). "Dysferlin deficiency has previously been associated with reduced capillary density and impaired angiogenic responses due to endothelial dysfunction and defective PECAM-1 stabilization." (PMID 41155239, 2025). "Increased PECAM-1 levels could be caused by PECAM-1 upregulation in lung endothelial cells or by inflammatory cells, which supports data on endothelial dysfunction." (PMID 37667267, 2023). "Higher circulating levels of PECAM-1, as occurring during inflammatory diseases such as ARDS, may serve as a diagnostic marker of endothelial dysfunction." (PMID 36084115, 2022). "Furthermore, our findings revealed that biomarkers reflecting fibroproliferative processes (VEGF, uPAR, galectin-3, E-selectin, and surfactant protein D), endothelial dysfunction (ANG-2, PECAM-1, and ICAM-1), and D-dimer were also associated with increased mortality risk." (PMID 41217548, 2025). "The biomarkers like ICAM-1 and PECAM-1 can be utilized in the detection of these endothelial damages because increased levels of these biomarkers are indicative of chronic inflammation and endothelial dysfunction, which are also the characteristics of the CNS in post-treatment BC patients." (PMID 35268306, 2022). "First, exposure of mouse ECs or HBMVECs to HIV-1 Tat protein significantly reduced CD31 intensity, also known as platelet endothelial cell adhesion molecule-1 (PECAM-1), suggesting Tat-induced endothelial dysfunction." (PMID 41282115, 2025). "EMVs with membrane molecules such as CD31 (PECAM-1, endothelial cells and platelet adhesion molecules) act as signalers/mediators of endothelial dysfunction and impaired endothelial permeability, promoting coagulation and inflammation." (PMID 40002365, 2025). "• Our study suggests that low levels of sPECAM1 are indicative of normal functioning of PECAM1, whereas higher circulating levels of sPECAM1, as occurs during inflammatory conditions such as sepsis, ARDS and VILI, could serve as diagnostic and prognostic biomarkers of endothelial dysfunction." (PMID 24588994, 2014). "No significant alterations in the serum markers of endothelial dysfunction/inflammation (spSelectin, seSelectin, PECAM-1, sICAM) or thrombosis (Thrombomodulin) were observed at 660 days post IR." (PMID 36982525, 2023). "The absence of endothelial PECAM-1 resulted in a decreased angiogenesis and might lead to endothelial dysfunction." (PMID 27781209, 2016).